KEAP1 (kelch like ECH associated protein 1)
Diseases named in the same sentence as KEAP1 in open-access papers (continued):
Sharing a sentence is not in itself a finding about the gene and the disease.
diabetes (continued). "It is possible that the oxidative stress in diabetes alters the redox-sending capacity of Keap1, thereby preventing the dissociation of Nrf2 from Nrf2-Keap1 complex." (PMID 28473877, 2017). "Another explanation of the altered binding between Nrf2 and Keap1 in diabetes includes diabetes-induced posttranslational or epigenetic modifications of retinal proteins, including Keap1." (PMID 28473877, 2017). "The MMF treatment did not change Nrf2 protein levels, but it significantly decreased the Keap1 protein expression compared with group with diabetes untreated and control group." (PMID 26955430, 2016). "After one month of diabetes induction, in cortex from group with diabetes, the Nrf2 and Keap1 protein expression were higher than that of the control group." (PMID 26955430, 2016). "Recently, the roles played by the Keap1-Nrf2 system, a famous anti-environmental press pathway, in the pathogenesis of diabetes mellitus and in the development of its complications have emerged as important research topics." (PMID 26552447, 2015). "Taken together, in this content, we established in vivo rat model of diabetes and in vitro high glucose incubated renal tubular cell and investigated the Sirt1/NF-κB/miR-29/Keap1/Nrf2 signal pathway in process of high glucose induced renal tubular injury." (PMID 26552447, 2015). "Abnormality of Keap1/Nrf2 is an important mechanism of impaired EC peroxidation in diabetes." (PMID 40232847, 2025). "Specifically, the induction of Nrf2 through Keap1-conditional knockout in pancreatic β-cells was found to suppress oxidative damage in pancreatic islets and significantly restore insulin secretion in the context of diabetes." (PMID 38671848, 2024). "Our findings suggest that the S-glutathionylation of Keap1 may be a key target for the prevention and treatment of β-cell dysfunction in individuals with prediabetes or diabetes." (PMID 38671848, 2024). "In addition, some compounds, including monomethyl fumarate and sulforaphane, reportedly alleviate the development of chronic diseases, such as diabetes, by activating Nrf2 through binding to the cysteine of Keap1." (PMID 39872153, 2024). "Activation of the Keap1-Nrf2 system could reduce the damage induced by oxidative stress and inflammation in diabetes." (PMID 38164478, 2024). "The modulation of the NRF2/KEAP1 pathway improves insulin sensitivity in diabetes and obesity." (PMID 35955599, 2022). "Collectively, we demonstrated that Rb1, which directly targeted Keap1 and p47phox in ECs, may be an attractive candidate for the treatment of atherosclerosis in diabetes." (PMID 36163178, 2022). "Similarly, structural activation of peripheral Nrf2 signaling via intrahepatic knockout of the Keap1 gene (encoding Kelch like ECH associated protein 1) alleviated obesity, diabetes, and liver steatosis 192,193." (PMID 35280695, 2022). "Actually, Keap1–Nrf2 system activation might be attenuated the damage by stress oxidative and inflammation in diabetes." (PMID 33468193, 2021). "Previous reports have also reported that diabetes-induced inflammation and oxidative stress could induce intrinsic antioxidant response through the Keap1/Nrf2 pathway." (PMID 32238837, 2020). "Xie also demonstrated that H2S attenuates diabetes-accelerated atherosclerosis, which may be related to inhibition of oxidative stress via Keap1 sulfhydrylation to activate Nrf2 signaling." (PMID 28842592, 2017). "However, the relationship between Keap1, Nrf2, and miR-200a in the diabetes-induced endothelium remains unclear and will be further explored in the future." (PMID 33736642, 2021). "The lower Keap1 protein levels in ARB after 6 wks of treatment suggests that the ability of ARB to ameliorate the insulin resistance-associated oxidative damage observed in OLETF rats and other models of diabetes and metabolic syndrome may be achieved by decreasing cytosolic Keap1." (PMID 29049981, 2018). "In addition, epigenetic modification of lens Keap1 has also been shown in diabetes." (PMID 28473877, 2017).
diabetes (continued). "The KEAP1/NRF2/antioxidant response element pathway is one of the most effective intracellular antioxidant stress pathways, playing a crucial role in diabetes-induced endothelial dysfunction." (PMID 41154476, 2025). "Its multifaceted impacts on the Nrf2/Keap1/ARE pathway, oxidative stress, and metabolic regulation highlight its potential as an adjunct in the treatment of diabetes and related cardiovascular disorders." (PMID 38524871, 2024). "By analyzing transcripts and protein activity of key components of the Keap1/Nrf2/HO-1 and AMPK/mTOR pathways, we further collected evidence of the mechanism by which oral polyphenol administration can significantly improve diabetes and its complications." (PMID 36832842, 2023). "Emerging studies have demonstrated that chronic oxidative stress, as occurs in diabetes, leads to the irregular inhibition of the Nrf2/ARE pathway by Keap1." (PMID 36499723, 2022). "Numerous studies demonstrated the dysregulation of Nrf2/Keap1/ARE pathways in many chronic diseases, including diabetes mellitus, obesity, and atherosclerosis." (PMID 35431967, 2022). "Keap1/Nrf2/ARE pathway plays an important role in the mediation of health recovery, oxidative stress, diabetes and its complications." (PMID 30781644, 2019). "It has been shown that Tertiary butylhydroquinone (TBHQ) is a positive agonist of Keap1/Nrf2/ARE system and has an effect of improving diabetes mellitus." (PMID 30781644, 2019). "2SC has been described in aging and diabetes, and its functional consequences have been reported for GAPDH and adiponectin in addition to the KEAP1/NRF2 pathway." (PMID 23499446, 2013). "KEAP1 is a well-known redox-sensitive protein and a unique E3 ligase targeting NRF2, which is involved in maintenance of redox and the progression of many diseases, including diabetes and cancer." (PMID 40190348, 2025). "Previous studies have confirmed that the KEAP1/NRF2 system could be an important therapeutic target for various diseases, including inflammatory diseases, diabetes, and neurodegenerative diseases." (PMID 38756779, 2024). "In a study with diabetes mellitus rats and with the MPC-5 cell line Icarin, a flavonoid extract isolated from Herba epimedii, increases mitophagy to inhibit NLRP3 inflammasome activation through the activation of the KEAP1/Nrf2 signaling pathway." (PMID 39334784, 2024). "The studies specifically using GYY4137 also reported the sulfhydration of KEAP1, activation of NRF2, and induction of genes regulated by NRF2 in experimental models of diabetes-accelerated atherosclerosis, sepsis, HIV-1 latency, renal ischemia/reperfusion injury, and liver damage." (PMID 35883901, 2022). "In an analysis of nephrectomy specimens from patients with diabetes, Nrf2 protein was increased, while Keap1 protein was equal compared to samples from patients without diabetes and normal kidney function." (PMID 35740009, 2022). "The Nrf2/Keap1/ARE signaling pathway is the primary transcriptional regulator of intracellular redox, and, in a mouse model of diabetes, induction of Nrf2 overexpression either by genetic Keap1 knockdown or by pharmacological means can enhance sensitivity to insulin and improve disease symptoms." (PMID 33167495, 2020). "The Keap1/Nrf2/ARE pathway plays a major role in health resilience including inflammatory diseases, neurodegenerative diseases, PD, AD, stroke, chronic kidney disease, atherosclerosis, diabetes, cardiovascular diseases and rheumatoid arthritis." (PMID 31165007, 2019). "Since Keap1/NRF2/ARE pathway is important in defensing mechanism against oxidative stress, managing this pathway may provide beneficial effects on chronic diseases such as cardiovascular diseases, diabetes, atherosclerosis, cancer, and neurodegenerative diseases." (PMID 32526964, 2020).
diabetes (continued). "Although previous studies showed that SFN activated NRF2 and ameliorated diabetes-induced testicular apoptotic cell death without knowing the expression of Keap1, we speculate that inhibition of KEAP1 function by SFN could be the mechanism through which SFN activated NRF2 in these studies." (PMID 28698767, 2017).
hepatocellular carcinoma (85 papers, 2010 to 2026). A malignant tumor that arises from hepatocytes. "For example, TRIM25 activated Nrf2 via ubiquitination-mediated Keap1 degradation, positively associated with Nrf2 expression and negatively with Keap1 expression in hepatocellular carcinoma." (PMID 40723303, 2025). "On the other hand, transfection with miR-141 mimics caused miR-141 activation and Keap1 suppression, which led to the re-activation of the Nrf2-dependent antioxidant pathways, inducing 5-FU resistance in hepatocellular carcinoma cells." (PMID 38970040, 2024). "Another interesting result was found in the SRP063938 project, where two hepatocellular carcinoma cell lines with KEAP1 mutations were used: Huh1, which has a missense mutation (p.N414Y), and Huh7, which has a silent mutation (p.Y334Y)." (PMID 39643653, 2024). "Enhancing the antitumor effects of sorafenib in sorafenib-resistant hepatocellular carcinoma cells by regulating Keap1/Nrf2-associated ferroptosis and EMT." (PMID 38239395, 2023). "Withaferin A enhances sorafenib sensitivity in sorafenib-resistant hepatocellular carcinoma cells by regulating the Keap1/Nrf2-associated epithelial-to-mesenchymal transition (EMT) and ferroptosis." (PMID 38239395, 2023). "It was recently reported that mutations in either KEAP1 or NRF2 were found in approximately 14% of hepatocellular carcinoma (HCC) cases." (PMID 28523248, 2017). "Withaferin A, a steroidal lactone isolated from the medicinal plant Ashwagandha [Withania somnifera (L.)Dunal], and Tiliroside, a flavonoid found in the herbs of Tribulus terrestris L., both modulate the Kelch-like ECH-associated protein 1 (Keap1)/Nrf2 pathway in hepatocellular carcinoma." (PMID 38239395, 2023). "The dual and opposite roles of NRF2 regulation-associated lncRNA (NRAL) and KEAP1 regulation-associated lncRNA (KRAL) have been recently outlined in hepatocellular carcinoma (HCC) cell lines." (PMID 33287295, 2020). "TRIM25 expression is positively associated with Nrf2 expression and negatively with Keap1 expression in hepatocellular carcinoma (HCC) xenografts and specimens." (PMID 31953436, 2020). "Oxidative stimulation induces phosphorylation of p62 at Ser28 by KHK-A in hepatocellular carcinoma cells (HCCs), thereby enhancing p62’s aggregation with Keap1 and Nrf2 activation." (PMID 40643536, 2025). "Tiliroside induces ferroptosis, making hepatocellular carcinoma (HCC) cells sensitive to sorafenib (SOF) through the Keap1/Nrf2 pathway." (PMID 40624553, 2025). "HECTD2 serves as an E3 ubiquitin ligase of KEAP1 to facilitate the antioxidative response and contributes to lenvatinib resistance in hepatocellular carcinoma." (PMID 39976163, 2025). "Conversely, acetyltransferase GCN5 inhibits hepatocellular carcinoma by facilitating p62 deacetylation and subsequent proteasomal degradation by Keap1." (PMID 40643536, 2025). "Our study also revealed that KEAP1 and related target genes were abnormally expressed in hepatocellular carcinoma cells and were closely related to drug resistance in hepatocellular carcinoma." (PMID 38938386, 2024). "Crucial signaling pathways, including Keap1-Nrf2, Wnt/β-catenin, and NF-κB, which are modulated by TRIM proteins, are intimately linked to the steatohepatitis, liver fibrosis, and hepatocellular carcinoma." (PMID 37867509, 2023). "TRIM25 has been reported to promote cell survival by ubiquitinating and degrading Keap1 in hepatocellular carcinoma." (PMID 35871160, 2022). "Contrary to 5-aza, Fumonisin B, a common toxic mycotoxins of cereal grains, activated NRF2/KEAP1 pathway by hypermethylating CpG islands in KEAP1 gene, consequently enhancing ROS production along with promoting cell membrane damage in human hepatoma cells." (PMID 35754474, 2022).
hepatocellular carcinoma (continued). "Sun et.al explained an increasing interaction of p62 and Keap1 after treating hepatocellular carcinoma cells with erastin, but the inherent mechanism of our study needs further investigation." (PMID 36274128, 2022). "TRIM25 expression was found positively associated with NRF2 expression in hepatocellular carcinoma, mechanistically, TRIM25 directly targeted Keap1 by ubiquitination and degradation, leading to NRF2 activation." (PMID 35087512, 2021). "In the present study, we show that lapatinib (2–20 μM) activates the Keap1-Nrf2 pathway in HepG2 cells, a hepatocellular carcinoma-derived cell line, in a concentration-dependent manner upon 24 h of treatment." (PMID 32694997, 2020). "In hepatocellular carcinoma, genomic modifications were mainly detected in the KEAP1 gene and in urothelial bladder carcinoma a probable link with NRF2 and thioredoxin signaling was observed." (PMID 32443774, 2020). "Hepatocellular carcinoma (HCC) is a life-threatening cancer, and the Kelch-like ECH-associated protein 1 (Keap1)/NF-E2-related factor 2 (Nrf2)/antioxidant response element (ARE) signalling pathway plays a crucial role in apoptosis resistance in cancer cells." (PMID 32273943, 2020). "This study aimed to evaluate the clinicopathological implications of the expression of Nrf2, pNrf2, and its regulator Keap1 in human hepatocellular carcinomas (HCCs)." (PMID 32751896, 2020). "In hepatocellular carcinoma, ovarian cancer, leukemia, and neuroblastoma cells, KEAP1 was targeted by miR-141, miR-23a, miR-432, miR-7, and miR-200a88,91–95." (PMID 32709863, 2020). "A similar relationship was observed between miR-141 and Nrf2/Keap1 pathway in hepatocellular carcinoma cells." (PMID 30498447, 2018). "For example, luteolin has been shown to inhibit the Keap1/Nrf2 signaling pathway in human hepatoma (HepG2), rat liver epithelial (RL-34), and mouse hepatoma (Hepa1c1c7) cells treated with dioxin (TCDD)." (PMID 29375370, 2017). "Similar findings were described in hepatoma cells, in which trehalose protected against oxidative stress via autophagy, which was regulated by the SQSTM1/p62- Kelch-like ECH-associated protein 1 (KEAP1)-NRF2 pathway." (PMID 40529415, 2025). "Besides, ROS levels in hepatocellular carcinoma cells were detected to assist in determining the oxidative stress role of Keap1 in LIHC." (PMID 38938386, 2024). "Additionally, tiliroside synergistically combines with sorafenib to inhibit Tank-binding kinase (TBK1) activity, prompting Keap1-mediated Nrf2 ubiquitination and degradation, leading to ferroptosis in hepatocellular carcinoma cells." (PMID 38239395, 2023). "It has been reported that activation of Nrf2 inhibited NAFLD and NASH through upregulating heme oxygenase-1 (HO-1) /NAD(P)H:quinone oxidoreductase 1 (NQO1)/glutathione S-transferase (GST), then promoted hepatocellular carcinoma by competing with Keap1 or through FGFR4–GSK3β signal pathway." (PMID 33114130, 2020). "The modified siRNAs, siKeap1-1* and siKeap1-2*, showed improved serum stability and a strongly reduced immune stimulatory potential in relation to the unmodified siRNAs, while their potency to suppress Keap1 expression in mouse hepatoma cells remained unchanged." (PMID 27814396, 2016). "HO-1 also elicits anti-ferroptotic effects in hepatocellular carcinoma (HCC) cells since Nrf2 activation inhibits ferroptosis via p62-mediated Keap1 degradation, upregulating the actions of Nrf2 on its target genes, HO-1 and FTH1." (PMID 41470866, 2025). "The results showed that under the same stimulation condition, the ROS level of hepatocellular carcinoma cells was significantly reduced after inhibiting Keap1 expression, suggesting that the high expression of Keap1 may promote oxidative stress of hepatocellular carcinoma cells." (PMID 38938386, 2024).
hepatocellular carcinoma (continued). "We examined the role of KEAP1 in regulating oxidative stress in hepatocellular carcinoma cells, and found that inhibiting KEAP1 expression could significantly reduce ROS levels in hepatocellular carcinoma cells, suggesting that high KEAP1 expression may promote cell dysfunction." (PMID 38938386, 2024). "Exposure of hepatocellular carcinoma cells (HCC) to ferroptosis-inducing compounds, such as elastin and sorafenib, promotes the nuclear accumulation of Nrf2 through the inactivation of KEAP1 by p62 expression." (PMID 35163335, 2022). "SQSTM1/p62, an oncogenic protein aberrantly accumulated in hepatocellular carcinoma (HCC), binds and sequestrates Keap1, leading to the prevention of NRF2 degradation." (PMID 34921137, 2021). "It has been revealed that Keap1–Nrf2 plays a central role in protecting hepatocellular carcinoma (HCC) cells against ferroptosis." (PMID 32951003, 2020). "In another investigation, Liu and colleagues demonstrated that by focusing on the Keap1-Nrf2 pathway, TRIM25 enhances hepatocellular carcinoma cell survival and proliferation." (PMID 39286246, 2024). "In hepatocellular carcinoma (HCC), TRIM25 has been found to target and degrade Keap1, consequently activating Nrf2 and fostering HCC cell proliferation by modulating the UPR signaling pathway and ERAD." (PMID 39080273, 2024). "In hepatocellular carcinoma, TRIM25 regulates endoplasmic reticulum homeostasis and mitigates oxidative stress by mediating the ubiquitination and degradation of Keap1." (PMID 38303029, 2024). "Selective inhibitors of the Keap1–phosphorylated-P62 interaction may function as therapeutic agents for hepatocellular carcinoma (HCC)." (PMID 36827109, 2023). "Consistent with the findings in the mouse model, in human hepatocellular carcinoma, p62- and KEAP1-positive aggregates are abundant, suggesting that successive NRF2 activation contributes to the development of hepatocellular carcinoma." (PMID 36230622, 2022). "TRIM25 contributes to the survival and the growth of hepatoma cells via targeting the Keap1-Nrf2 pathway, and highly expressed TRIM25 predicts the unfavorable prognosis of patients with liver carcinoma." (PMID 33506106, 2021). "Nevertheless, this mechanism has yet to be solved in that ferroptosis inducers aid in p62′s binding to Keap1 to competitively hinder the interaction between Keap1 and NRF2, facilitating NRF2 in hepatocellular cancer (HCC)." (PMID 33419148, 2021). "Cumulative evidence indicated that several natural molecules exerted hepatoprotective effects through activating the Keap1–Nrf2 pathway, which implied that the activation of this pathway might protect against erastin-induced ferroptosis in hepatocellular carcinoma (HCC) cells." (PMID 32951003, 2020). "First, we analysed the expression of SET8, Keap1, and Nrf2 by immunohistochemical staining in tumour tissues and adjacent nontumour tissues from hepatocellular carcinoma patients who underwent a surgical resection." (PMID 32273943, 2020). "We suggest that loss of GSTZ1‐1 results in the accumulation of the oncometabolite SA, alkylation of KEAP1, and NRF2 activation, promoting IGF1R transcription by recruiting SP1 to its promoter, which promotes the antiapoptotic pathway of hepatoma cells in vitro and in vivo." (PMID 31267557, 2019). "Increased levels of miR-141 expression in hepatocellular carcinoma cells such as HepG2, SMMC-7721, and HuH7 cell lines has shown to downregulate Keap1 expression via the Keap1 3′ untranslated region (3′ UTR), resulting in transcriptional activation of Nrf2-dependent HO-1 gene." (PMID 30498447, 2018). "Moreover, liver-specific knockout of Keap1 (e.g., Keap1FA/FA; Alb-Cre mice) has not been reported to result in hepatocellular carcinoma, despite the animals having been first reported in 2006." (PMID 33276631, 2020).